IL6 (interleukin 6)
Diseases named in the same sentence as IL6 in open-access papers (continued):
Sharing a sentence is not in itself a finding about the gene and the disease.
COVID-19 (continued). "Moreover, during active severe COVID-19, increased plasmablast frequency directly correlated with IL6 level, which was instead inversely associated with cDC2." (PMID 34867943, 2021). "In pediatric COVID-19 reports, increasing levels of serum interleukin (IL)-6 and IL-10 are also associated with greater COVID-19 disease severity, although the levels of these cyto- kines are not significantly different between infected children with and without elevated serum liver enzymes." (PMID 33777864, 2021). "Here, we highlight the distinct contributions of IL-6 signaling to the pathogenesis of several types of cytokine storms and discuss potential therapeutic strategies for the management of cytokine storms, including those associated with sepsis and COVID-19." (PMID 34253862, 2021). "ADRB2, FOS, and IL-6 were found to be associated with COVID-19 inflammation." (PMID 35127768, 2021). "Several studies had reported that IL-6 was involved in the pathophysiological process of COVID-19; therefore, we performed a subgroup analysis in patients who were tested for IL-6 to explore whether IL-6 could be an independent risk factor at our center." (PMID 33795768, 2021). "Interestingly, among patients with myocardial infarction (MI), the D-allele of ACE is associated with higher levels of IL-6, which has been associated with worse outcomes of COVID-19." (PMID 33390179, 2021). "While many trials are still ongoing, a recent meta-analysis revealed, that therapeutic IL-6 (receptor) antagonists are effective in reducing mortality in COVID-19 patients, while the risk of side effects is higher, highlighting the potential but also the need for better therapies." (PMID 34943881, 2021). "Consistent with this, EBV infection was detected in COVID-19 patients, associated with increased risk of severe COVID-19 symptoms and fatal outcome, and correlated increased levels of IL-6." (PMID 34248910, 2021). "Besides, it has been reported that the pro-inflammatory cytokine IL-6 and organ damage biomarkers, such as D-dimer and NT-proBNP were risk factors for death of adults with COVID-19." (PMID 34521370, 2021). "The present study suggests that an individual's IL-6 genotype underlies COVID-19 outcome and may be used to guide IL-6 blockade therapy in Asian patients." (PMID 34634929, 2021). "In COVID-19, adiposity is associated with a preponderance of pro-inflammatory cells in hypertrophic adipocytes, that contribute to increases in serum cytokines, such as IL-6, TNF-alpha and CRP." (PMID 34383798, 2021). "In conclusion, PaO2/FiO2 and IL-6 could potentially serve as independent risk factors for predicting death in COVID-19 patients requiring intensive care, and the prognosis of patients could possibly be judged according to the change in the trend of IL-6 level." (PMID 33795768, 2021). "Furthermore, IL-6 levels have been associated with COVID-19 progression into severer stages and mortality." (PMID 34456928, 2021). "The levels of interleukin-6 (IL-6), D-dimer, and lymphocytes could help clinicians to identify COVID-19 patients with poor prognoses early and identify high-risk patients." (PMID 34778296, 2021). "Of note, IL-6, a major pro-inflammatory cytokine produced mainly by macrophage and T-helper 2 (Th2) cells, has been demonstrated to be significantly associated with the development or severity of COVID-19 in many studies." (PMID 33480978, 2021). "In addition, along with age and levels of troponin, creatinine and IL-6, severe vitamin D deficiency emerged as an independent survival factor in COVID-19 patients." (PMID 32772324, 2021). "IL-6 is one of the key cytokines implicated in COVID-19 severity and patient mortality." (PMID 34159203, 2021). "Finally, elevated serum levels of proinflammatory cytokines, such as IL-6 and IL-1β, in critically ill patients with COVID-19 were found to be associated with abnormal coagulation parameters, which are caused by endothelial dysfunction." (PMID 34253862, 2021).
COVID-19 (continued). "COVID-19 causes the production of IL-6, possibly due to the induction of TLR pathways." (PMID 34659656, 2021). "Elevated serum IL-6 levels on admission have been associated with severe COVID-19, and IL-6 is thought to underlie the pathogenesis of the cytokine release syndrome responsible for high mortality in COVID-19." (PMID 34123422, 2021). "Therefore, IL-6 serum level can be used as a predictor for rapid diagnosis of COVID-19 patients with a high risk of deterioration." (PMID 34806090, 2021). "Thus, IL-6 serum level is augmented in hypogonadism patients that increase their susceptibility for COVID-19 severity." (PMID 34568081, 2021). "The association of SAM and SAH with IL-6 suggests that they play an important role in transmethylation toward the development of cytokine imbalance in COVID-19, but more research is needed to identify the pathogenetic and therapeutic potential for correcting SAM levels." (PMID 34956420, 2021). "Notably with SARS-CoV-2 infection we observed induction of IL-6, a pro-inflammatory cytokine implicated in the pathogenesis of COVID-19, only within infected cells at 24 and 48 hours post-infection." (PMID 33507952, 2021). "The COVID-19 cytokine profile of patients is closely associated with cytokine release, indicating macrophage activation, and an increase in the level of cytokines such as the TNFα, IL-6 and interferon-gamma (IFN-γ)." (PMID 33927728, 2021). "In addition, the high IL-6 levels in COVID-19 patients were associated with a decrease in CD4+ and CD8+ T cells." (PMID 34123873, 2021). "Reduced IL-6 and IL-10 levels were found in 95% and 19% of patients, respectively, suggesting that COVID-19 may have a role in cellular immune deficiency." (PMID 34122618, 2021). "PaO2/FiO2 and IL-6 could potentially serve as independent risk factors for predicting death in COVID-19 patients requiring intensive care." (PMID 33795768, 2021). "Also, we have shown that hydroxychloroquine is an effective TLR8 inhibitor attenuating the TLR8-induced IL-6 release, a cytokine associated with COVID-19 progression and mortality." (PMID 34456928, 2021). "This is an important finding as it may help develop a strategy for treating COVID-19 since inflammation and blood clotting are linked to regulatory molecules IL-6 and ICAM-1 induced by VPA." (PMID 34674775, 2021). "Indeed, we demonstrated that plasma A1AT levels were associated with COVID-19 severity and with IL-6, a cytokine that has been implicated in COVID-19 pathology and as a biomarker for disease severity." (PMID 33969249, 2021). "IL-6 is implicated in the pathogenesis of some infectious diseases such as COVID-19." (PMID 34368012, 2021). "Altogether, our data suggest that high levels of circulating IL-6, TNF, and IL-10 might be associated with the severity of COVID-19, while only an increased level of IL-6 might be related to the severity of SARS and MERS." (PMID 34046036, 2021). "Severe COVID-19 cases may benefit from the IL-6 pathway inhibition, given the associated cytokine release syndrome (CRS) and sHLH-like serum cytokine elevations." (PMID 34439868, 2021). "A pathogenic role for IL-6 and its receptor in COVID-19 has been described." (PMID 33968010, 2021). "Therefore, D-dimer, blood glucose, and IL-6 should be monitored to prevent COVID-19-associated complications." (PMID 34829418, 2021). "In this case, single nucleotide polymorphisms (SNPs) in ACE2 and IL-6 genetic polymorphisms may be related to HF in patients with COVID-19." (PMID 33404925, 2021). "Actually, lung inflammation caused by COVID-19 can be aggravated because of macrophage activation syndrome and its production of several inflammatory cytokines (IL-6, IL-7, TNF), chemokines (CCL2, CCL3, CXCL10) and the soluble form of α-chain of the IL-2 receptor." (PMID 33859644, 2021).
COVID-19 (continued). "In different backgrounds, IL-6 has been associated with oxidative stress, inflammation, endothelial dysfunction, and thrombogenesis which are characteristic features of Severe COVID-19 cases caused by excessive myeloid cell activation." (PMID 34262570, 2021). "Raised inflammatory responses in COVID-19 individuals with advanced disease reflects the induction of a cytokine storm—up-regulation of IL-6, G-CSF, IL-1RA, and MCP1 has been shown to be associated with severe outcomes leading to mortality in patients with COVID-1931." (PMID 34824360, 2021). "Therefore, it is evident that COVID-19 shares the IL-6/JAK/STAT3 axis, and it is associated with several comorbid conditions such as cancers, CVDs, and CKDs, as found in our analyses." (PMID 34067609, 2021). "IL-6 >142.5 pg/mL, IL-10 >10.8 pg/mL, IL1β > 4.68 pg/mL, sIL-2rα >804.5 pg/mL, IL-1Ra >88.4 pg/mL, and IL-18 > 144 pg/mL values were associated with the development of critical COVID-19 in the age-adjusted univariate analysis." (PMID 34422145, 2021). "Multivariate analyses showed that higher levels of IL-6, IL-8, and IL-10 remained significantly correlated with shorter survival time and that the amount of Ts cells was negatively associated with the possibility of death in COVID-19 patients." (PMID 33542929, 2021). "Older age, male sex, underlying illness, sustained fever status, abnormal liver and renal functions, excessive expression of IL-6, lymphopenia, and selective loss of peripheral lymphocyte subsets were related to disease deterioration and clinical outcome in COVID-19 patients." (PMID 34123873, 2021). "Thus, 4 F attenuates in vitro SARS-CoV-2 replication, associated apoptosis in epithelial cells and secretion of IL-6, a major cytokine related to COVID-19 morbidity." (PMID 34494942, 2021). "COVID-19 has also been associated with elevated levels of IL-6, which in animal models may trigger the development of AT1R-Ab." (PMID 34788328, 2021). "Using the resulting K-ML2 (AT) clone 35 for SARS-CoV-2-infection or its subclone 35–40 for IL-6 productivity, it was possible to evaluate the potential of sera from severe COVID-19 patients to cause ADE and to stimulate IL-6 production upon infection with SARS-CoV-2." (PMID 34887501, 2021). "Additionally, a potential caveat to using HbA as a countermeasure for COVID-19-induced hypoxia is that hemoglobin has been reported to cause stimulation of IL-6, IL-8, and tumor necrosis factor-α from leukocytes in whole blood." (PMID 34445747, 2021). "However, the functional role and molecular mechanisms of IL-6 in the pathogenesis of COVID-19 associated AKI remain largely unclear." (PMID 33907513, 2021). "Second, frailty involving the process of complex chronic inflammation and proinflammatory cytokines, such as C-reactive protein, tumor necrosis factor (TNF)-a, interleukin (IL) or interleukin-6, exacerbates the risk of mortality when patients contract COVID-19." (PMID 33731018, 2021). "We analyzed interleukin (IL)-6 by human-specific enzyme-linked immunosorbent assay and a large set of lymphocyte subpopulations by flow cytometry in 274 COVID-19 patients hospitalized from September 2020 to May 2021." (PMID 34556132, 2021). "Moreover, it seems that Sitagliptin has proven efficacy against acute respiratory distress syndrome (ARDS), the common causes of COVID-19-related death, because this drug inhibits IL-6, IL-1, and TNF in individuals with lung injury." (PMID 34015003, 2021). "High expression of IL-6 has been noted in critically ill patients with COVID-19, and IL-6 expression could be used to assess risk." (PMID 33520118, 2021). "In parallel, a recent report showed enhanced TREM2 protein levels in the CSF of a patient with COVID-19-associated encephalopathy, along with increased protein levels of IL6, IL8, and TNF in both CSF and serum (see section “Microglia Respond to the Systemic Inflammatory Response in COVID-19”)." (PMID 33737867, 2021).
COVID-19 (continued). "In addition, increased IL-6 levels were found to be associated with decreased survival time of COVID-19 patients, and IL-6 level was suggested to serve as a biomarker of CRS severity." (PMID 34884813, 2021). "Lymphopenia, thrombocytopenia, and elevated levels of interleukin-6, ferritin, D-dimer, aspartate aminotransferase, C-Reactive-Protein, procalcitonin, creatinine, neutrophils and leucocytes were associated with severe and fatal COVID-19 cases." (PMID 34185801, 2021). "Since cytokine storms have been established as an important pathogenic mechanism of mortality in severe COVID-19, the blocking of IL-6 activity may offer a promising therapeutic target in severe COVID-19." (PMID 34006330, 2021). "These low IFN levels were associated with a persistent viral load in the blood and an exacerbated inflammatory response (overproduction and release of tumor necrosis factor-α [TNF-α] and IL-6), which may be a hallmark of severe COVID-19." (PMID 34593760, 2021). "Although these results may explain the association of SAM levels with IL-6 in COVID-19 patients, the association of SAH with IL-6 remains unclear, since SAH is a transmethylase inhibitor that should cause a global decrease in DNA methylation." (PMID 34956420, 2021). "Besides, LMWH treatment of COVID-19 patients was found to considerably reduce plasma levels of IL-6, a critical cytokine linked to the disease’s immunopathogenesis, in a retrospective clinical investigation." (PMID 35062238, 2021). "However, it has been reported that inborn errors of type I IFN immunity are associated with severe COVID-19 since the low type I IFN activity triggers IL6 and NF-α mediated pro-inflammatory responses and cytokine storm." (PMID 34067609, 2021). "The viral load of SARS-CoV-2 has been linked to blood levels of IL-6 in COVID-19 patients, suggesting that this cytokine may have a role in the development of ARDS." (PMID 34299201, 2021). "Observationally associations of IL-6 with COVID-19 have been seen." (PMID 34163532, 2021). "Thus, the use of therapeutic agents targeting IL-6, such as tocilizumab, has been studied in hospitalized patients with COVID-19 and showed mortality benefits and associated with clinical improvement." (PMID 34724920, 2021). "It was also determined by the presence of inflammatory markers associated with COVID-19, such as elevated lactate dehydrogenase (OR 1.30, 95% CI 1.16–1.47; p < 0.05), interleukin-6 (OR 1.73, 95% CI 1.16–2.59; p < 0.05), or ferritin levels (OR 1.93, 95% CI 1.59–2.35; p < 0.05)." (PMID 34749645, 2021). "Level of IL-6 gene expression is known to be associated with the − 174 G/C polymorphism (rs1800795), and we considered the possibility that this variant is associated with severe COVID-19 and poor outcome." (PMID 34775962, 2021). "Death from adult respiratory distress syndrome as a result of COVID-19 has been linked to a prolonged increase in IL-6 and IL-1-like cytokines that results in hyper-inflammation, known generally as cytokine storm or, more specifically, macrophage activation syndrome." (PMID 34225749, 2021). "Exacerbated ROS mediate the release of IL-6 (a pro-inflammatory cytokine linked to increased disease severity and mortality in diabetic COVID-19 patients) via the accumulation of intracellular Ca2+ due to the opening of Ca2+ release-activated Ca2+ (CRAC) channels." (PMID 34157054, 2021). "These shared cytokines logically included molecules that have been implicated in COVID-19 pathogenesis such as IL-6, eGFR, vitamin D3, and fibrinogen, as well as molecules that are more generally associated with inflammation/infection, such as VES, D-dimer, PCR, and iron." (PMID 34683357, 2021). "IL-6 can be considered an early biomarker in the prediction of clinical deterioration of patients with moderate-to-severe COVID-19, especially when associated with other biochemical and physiological parameters such as SpO2/FiO2 ratio and C-reactive protein itself." (PMID 37386621, 2021).
COVID-19 (continued). "COVID-19 associated myopathy with severe proximal and bulbar weakness is characterized by elevated levels of IL-6 and Creatine PhosphoKinase (CPK) and the histological features of COVID-19 are mostly anecdotic and only a few case reports have been recently published on this subject." (PMID 34025446, 2021). "Studies have stated that this may be linked to hyperglycemia playing a detrimental role in overproduction of interleukin-6 (IL-6), which has been associated with increased lung infiltration and severity of COVID-19." (PMID 33842709, 2021). "Our study focused on IL-6 due to its reported unique role in the cytokine storm occurring in patients with COVID-19, its good correlation to disease severity, the risk of needing mechanical ventilation, or death, and most importantly, because it can be used as a pharmacological target." (PMID 33679753, 2021). "High serum levels of IL-6 have been widely described as a hallmark of severity in COVID-19." (PMID 34422145, 2021). "Our data on lymphocytopenia, WBC and IL-6 support the hypothesis that severe cytokine release syndrome (‘cytokine storm’) causes more profound respiratory disease in COVID-19, which is already established in ARDS generally." (PMID 32941548, 2020). "• Significantly higher levels of IL-6, IL-8, and TNF-α were observed in serum of COVID-19 patients as compared to the healthy control or patients with multiple myeloma.• IL-6, IL-8, and TNF-α were associated with worst disease outcome and suggested as the predictive indicators of the disease." (PMID 33335518, 2020). "Indeed, several key inflammatory cytokines associated with hypertension (TNF-α, MCP-1, and IL-6) overlap those elevated in COVID-19." (PMID 32848776, 2020). "In COVID-19, adding to the blood clotting risk from increased IL-6, SARS-CoV-2 can infect, replicate and induce endothelial cell death, compromising the continuity of the luminal vascular surface; a perturbed endothelium can actively participate in pro-coagulant reactions." (PMID 32629875, 2020). "More importantly, our studies indicated that IL-6 and IL-8 may be differentially used as biomarkers for the severity and prognosis of the COVID-19 associated diseases." (PMID 33488599, 2020). "Taken together, these reports support that increased cytokine levels may be associated with worse clinical presentation and outcome in COVID-19, of which IL-6 may be an important driving force of the cytokine storm." (PMID 33505321, 2020). "Moreover, single cell analysis of PBMCs has reported the presence of a monocyte subset unique to severe COVID-19 patients that is enriched in genes encoding a range of cytokine storm related cytokines such as IL-1β, IL-6, and TNF-α." (PMID 33123152, 2020). "Additionally, TLR4 is protective in the MHV-1 SARS respiratory model and over-activation of TLR4 by phospholipids is linked to lung damage and increased levels of IL-6 in COVID-19 patients." (PMID 33377937, 2020). "COVID-19 related publications show the highest association with IL-6; this may be the result of a focus of current research on cytokine storms in COVID-19 infections." (PMID 32746922, 2020). "The dramatic need of treatment options for SARS-CoV-2 infection, the instrumental role played by IL-6 in the pathogenesis of COVID-19-associated CRS, and the well-known safety profile of the agent prompted the off-label use of TCZ early in the course of the pandemic." (PMID 33110739, 2020). "As all patients are lymphopenic, the neutrophil-to-CD8+ T cell ratio, counts of CD4 and CD8 T cells, and cytokine IL-6 and IL-10 can be identified as the most powerful prognostic factors for the progression of disease from mild to severe CoV-2 infection." (PMID 32781571, 2020). "The severity of pulmonary complications in COVID-19 is closely linked to IL-6 peak levels." (PMID 33392263, 2020). "In particular, circulating IL-6 levels are closely associated with the severity of COVID-19." (PMID 32722596, 2020).